ARF6 (ARF GTPase 6)
Diseases named in the same sentence as ARF6 in open-access papers (continued):
Sharing a sentence is not in itself a finding about the gene and the disease.
chordoma (2 papers, 2021 to 2022). Chordomas are rare malignant tumors arising from embryonic remnants of the notochord in axial skeleton. "In the present study, we sought to clarify the regulatory role of the lncRNA MDFIC-7/miR-525-5p/ARF6 axis in chordoma progression and examine the potential underlying mechanisms." (PMID 34621682, 2021). "Overexpression of ARF6 could abate the suppressive influence of XIST deficiency on chordoma cell growth, metastasis, and glycolysis." (PMID 35899235, 2022). "This is the first report to demonstrate that the XIST miR-320d/ARF6 axis contributed to the tumorigenesis of human chordoma." (PMID 35899235, 2022). "ADP-ribosylation factor 6 (ARF6) is widely expressed in mammalian cells and is used as a tumor-promoting gene in chordoma." (PMID 35899235, 2022). "In this work, we demonstrated that XIST was highly expressed in chordoma, and its silencing limited chordoma cell proliferation, metastasis, and glycolysis via regulating the miR-320d/ARF6 axis." (PMID 35899235, 2022). "Overall, these results suggested that ARF6 overexpression abated inhibitory effects of XIST downregulation on chordoma cell proliferation, metastasis, and glycolysis." (PMID 35899235, 2022). "In conclusion, our results proved that XIST knockdown suppressed chordoma cell growth, metastasis, and glycolysis as well as inhibited tumor growth in vivo by regulating the miR-320d/ARF6 axis." (PMID 35899235, 2022). "XIST knockdown inhibited chordoma progression via regulating the miR-320d/ARF6 axis, providing a novel insight into chordoma pathogenesis." (PMID 35899235, 2022). "Our results showed that inhibition of lncRNA MDFIC-7 expression or transfection of miR-525-5p mimic repressed the colony forming activity of chordoma cells, but this effect was reversed by co-expression of ARF6." (PMID 34621682, 2021). "In this study, we demonstrated that lncRNA MDFIC-7 knockdown suppressed cell proliferation, tumorigenicity and the Warburg effect (aerobic glycolysis) of chordoma cells both in vitro and in vivo through inhibiting the expression of ARF6." (PMID 34621682, 2021). "We demonstrate that the lncRNA MDFIC-7/miR-525-5p/ARF6 axis contributes to the tumorigenesis of human chordoma and facilitates the Warburg effect and cancer progression." (PMID 34621682, 2021). "Our results indicated that the effect of lncRNA knockdown on suppressing tumor progression and aerobic glycolysis of chordoma was achieved by modulating ARF6 expression via the lncRNA MDFIC-7/miR-525-5p axis." (PMID 34621682, 2021). "In summary, our study provides the first identification of the lncRNA MDFIC-7/miR-525-5p/ARF6 regulatory network in cell proliferation and glucose metabolism in chordoma." (PMID 34621682, 2021). "To determine whether XIST regulated chordoma cell behaviors by targeting ARF6, we performed rescue experiments in U-CH1 and JHC7 cells." (PMID 35899235, 2022). "According to these findings, we hypothesized that ARF6 might be involved in chordoma development via regulating miR-320d and ARF6." (PMID 35899235, 2022). "•XIST knockdown inhibited chordoma progression by downregulating ARF6." (PMID 35899235, 2022). "•XIST positively upregulated ARF6 expression via sponging miR-320d in chordoma cells." (PMID 35899235, 2022). "ARF6 protein expression was also increased in chordoma tissues." (PMID 35899235, 2022). "In addition, the relationships among XIST, miR-320d, and ARF6 in chordoma cells were also investigated using bioinformatic databases and a series of experiments." (PMID 35899235, 2022). "Furthermore, overexpression of ARF6 reversed the inhibitory effects of XIST knockdown on chordoma cell proliferation, migration, invasion, and glycolysis." (PMID 35899235, 2022). "Here, we also observed upregulation of the ARF6 expression in chordoma tissue samples." (PMID 35899235, 2022).
chordoma (continued). "Dual luciferase reporter assay revealed that miR-525-5p mimic transfection inhibited the activity of the luciferase reporter harboring the wild-type ARF6 3′UTR in chordoma cells, while co-transfection with lncRNA MDFIC-7 blocked the inhibitory effect of miR-525-5p mimic on luciferase activity." (PMID 34621682, 2021). "Our mechanistic studies identified ARF6 mRNA as a direct target of miR-525-5p in chordoma cells." (PMID 34621682, 2021). "The lncRNA MDFIC-7/miR-525-5p/ARF6 axis regulates chordoma progression and the Warburg effect in chordoma, suggesting that lncRNA MDFIC-7 and miR-525-5p could be promising therapeutic targets for the treatment of chordoma." (PMID 34621682, 2021). "A significant correlation between lncRNA MDFIC-7 and ARF6 expression in chordoma was found." (PMID 34621682, 2021). "Consistent with the ECAR results, lncRNA MDFIC-7 knockdown enhanced OCR in chordoma cells, and the promotion of OCR was reversed by ARF6 overexpression." (PMID 34621682, 2021). "The expression of ARF6 mRNA was dramatically inhibited by lncRNA MDFIC-7 knockdown in U-CH1 and U-CH2 chordoma cells." (PMID 34621682, 2021). "Overexpression of ARF6 reversed the inhibitory effect of lncRNA MDFIC-7 knockdown on cell proliferation and the Warburg effect in chordoma cells and xenograft tumors." (PMID 34621682, 2021). "The expression of ARF6 was evaluated and found increased in chordoma tissues compared to adjacent non-tumor tissues." (PMID 34621682, 2021). "Importantly, an increase in ARF6 expression was found in chordoma tissues, and ARF6 overexpression reversed the suppressive effect of MDFIC-7 silencing on proliferation and aerobic glycolysis of chordoma cells." (PMID 35899235, 2022). "However, the function of ARF6 in chordoma has not been examined." (PMID 34621682, 2021).
clear cell renal cell carcinoma (2 papers, 2016 to 2024). "Another GEF, exchange factor for Arf6 (EFA6), which interacts with the GTP-bound G-protein subunit alpha 12 released from G-protein-coupled receptors mediated by lysophosphatidic acid, also activates ARF6 in clear cell renal cell carcinoma." (PMID 39682280, 2024).
COVID-19 (2 papers, 2023). A disease caused by infection with severe acute respiratory syndrome coronavirus 2. "Altogether, these data highlight ARF6 as a potential target in the development of therapeutics against COVID-19." (PMID 37342971, 2023).
cutaneous melanoma (2 papers, 2021 to 2024). A primary melanoma arising from atypical melanocytes in the skin. "The small GTPase adenosine diphosphate-ribosylation factor 6 (ARF6) has been shown to control cutaneous melanoma invasion via activation of both PI3K and AKT and a relationship has been found between ARF6 hyperactivation and metastasis of cancer." (PMID 33807778, 2021).
cyst (2 papers, 2021 to 2024). A sac-like closed membranous structure that may be empty or contain fluid or amorphous material. "Furthermore, it has been reported that in 3D Matrigel culture, MDCK cells depleted of the small GTPase Arf6 form an inverted cyst, whose inversion is restored by epidermal growth factor‐elicited Rac1 activation and by expression of a constitutively active form of Rac1." (PMID 39377417, 2024).
diabetic retinopathy (2 papers, 2023 to 2025). "NAV-2729, a small molecule inhibitor of ARF6, was also shown to abrogate vascular permeability and pathological angiogenesis in a rat model of diabetic retinopathy." (PMID 37834383, 2023). "In addition, in a mouse model of diabetic retinopathy, endothelium-specific ablation of ARF6 protected against vascular leakage by reducing VEGFR2 signaling capacity." (PMID 37834383, 2023).
endometrial cancer (2 papers, 2023 to 2025). Primary or metastatic malignant neoplasm involving the endometrium (mucous membrane that lines the endometrial cavity).
epilepsy (2 papers, 2020 to 2024). A brain disorder characterized by episodes of abnormally increased neuronal discharge resulting in transient episodes of sensory or motor neurological dysfunction, or psychic dysfunction. "Furthermore, ARF6 KD in the DG increased seizure susceptibility in an induced epilepsy model." (PMID 31907062, 2020). "Viewed together, our results suggest that modulating ARF6 and its regulators could be a therapeutic strategy against brain pathologies involving hippocampal network dysfunction, such as epilepsy." (PMID 31907062, 2020).
esophageal carcinoma (2 papers, 2022 to 2024). A primary or metastatic malignant neoplasm involving the esophagus. "Our findings suggest that the ARF6 gene expression is up-regulated highest in oesophageal cancer." (PMID 35143561, 2022). "This analysis revealed a significant increase in ARF6 mRNA expression in oesophageal cancer, which is confirmed by analysing ARF6 protein expression in oesophageal adenocarcinoma (EAC) tissue microarray cores by immunohistochemistry using an anti-ARF6 antibody." (PMID 35143561, 2022).
HCMV infection (2 papers, 2018). "To determine if CIE cargos are differentially sorted into different vesicular domains of the ARF6+/EEA1− heterotypic SEs in HCMV infection, we exploited the ability of TRE17 to induce dissociation of ARF6 and EEA1 membranes into distinct populations." (PMID 30042195, 2018). "Apparently, overactivation of Arf6 is essential for the progression of CMV infection." (PMID 30564576, 2018). "HCMV infection hijacks cargo sorting into EEA1 or ARF6 membranes in heterotypic SEs." (PMID 30042195, 2018). "Dysregulation of the Arf6 axis has been recently described in the early phase of HCMV infection." (PMID 30564576, 2018). "Expression of TRE17, a ubiquitin-specific protease known for regulating both ARF6 and CIE cargo trafficking to the PM, rescued CD147 and, to a lesser extent, CD59 trafficking from SEs in the context of HCMV infection." (PMID 30042195, 2018). "Therefore, we propose a model whereby HCMV infection directs the sorting of cargo, such as MHC-I and CD98, from ARF6-positive domains into EEA1-positive domains in heterotypic SEs, which accumulate during infection." (PMID 30042195, 2018). "This appears to be a novel mechanism for regulating both the timing and precision of endocytic sorting events and a method of control that may not be restricted exclusively to ARF6 trafficking or HCMV infection." (PMID 30042195, 2018).
head and neck squamous cell carcinoma (2 papers, 2020 to 2023). A squamous cell carcinoma that arises from any of the following anatomic sites: lip and oral cavity, nasal cavity, paranasal sinuses, pharynx, larynx, and salivary glands. "Indeed, ARF6 plays a role in EGFR-driven tumorigenesis, where it acts downstream of EGFR and GEP100 to induce invasion and malignancy in breast cancer, EMT in head and neck squamous cell carcinoma (HNSCC) and invasion and prognosis in NSCLC." (PMID 33302515, 2020).
Hypertension (2 papers, 2016 to 2022). The presence of chronic increased pressure in the systemic arterial system. "Studies reported that HIF-1alpha and ARF6 regulate the role of vascular endothelial growth factors in pulmonary arteries, showing a vital part of the pathogenesis of hypertension and hypoxic artery remodeling." (PMID 35205232, 2022). "The pathway enrichment analysis revealed the roles of the HIF-1-α transcription; endothelin; GPCR-binding ligand; and signaling pathways of EGF, PIk3, Arf6, S1P1, and PGDF in hypertension." (PMID 35205232, 2022).
metastatic disease (2 papers, 2020 to 2023). "Linc-ROR was dramatically upregulated in TNBC and in metastatic disease, apparently through regulation of the miR-145/ARF6 (ADP ribosylation factor 6) axis." (PMID 36827545, 2023).
osteosarcoma (2 papers, 2023). A usually aggressive malignant bone-forming mesenchymal neoplasm, predominantly affecting adolescents and young adults. "Strikingly, our study uncovers CNK2-dependent ARF6 signalling as a novel mechanism underlying the pro-motility function of AXL in U2OS osteosarcoma cells." (PMID 37322019, 2023). "Using osteosarcoma cells to decipher the underlying mechanism, we discovered a CNK2-dependent signalling axis, triggered by the RTK AXL, that coordinates the activity of ARF6, RAC1, and RHOA GTPases." (PMID 37322019, 2023). "The signaling pathways involved in tumor progression of Osteosarcoma are the FOXM1 transcription pathway, ATM signaling pathway, FAK mediated signaling events, Arf6 signaling events, Class 1 PI3K signaling events, mTOR signaling pathway, and Integrin family cell surface interactions." (PMID 37081847, 2023).
papillary thyroid cancer (2 papers, 2020 to 2024). "Stratification of papillary thyroid cancer (THCA) TCGA expression data using quartile values (Q3Q4 vs Q1Q2) further highlighted the potential clinical relevance for 5 of these NIS interactors (AP2A2, ARF6, CTTN, HLA-A and RAB5C) on disease recurrence following RAI treatment (P < 0.05)." (PMID 37921808, 2024).
schizophrenia (2 papers, 2012 to 2022). A major psychotic disorder characterized by abnormalities in the perception or expression of reality. "Some vesicle recycling‐associated proteins (such as ARF6) are responsible for several neurologic and psychiatric diseases including Schizophrenia." (PMID 35899365, 2022).
squamous cell carcinoma (2 papers, 2016 to 2019). A carcinoma arising from squamous epithelial cells. "ADAP1, a GTPase-activating protein (GAP) for the small GTPase ARF6, is a strong predictor of poor survival in early-stage squamous cell carcinoma patients and a critical mediator of TGF-β-induced invasive cell migration by facilitating basement membrane breakdown." (PMID 31792062, 2019).
Ataxia (1 paper, 2009). Ataxia refers to impaired coordination of voluntary muscle movement. "A-RAF involvement in ARF6 dependent endocytic recycling provides a new perspective for explaining the phenotype of A-RAF knock out mice, which exhibit severe neurological defects such as ataxia, rigidity of the musculature and continuous tremor." (PMID 19247477, 2009).
bladder cancer (1 paper, 2016). "This is further conserved in oncogenic H-Ras containing bladder cancer T24 cells, which express anchorage independent active Ral that supports Arf6 activation." (PMID 27269287, 2016). "Functionally, RalBP1 mediated regulation of Arf6 downstream of Ral does affect the plasma membrane delivery of raft microdomains in WTMEFs and anchorage independent Erk signalling in T24 bladder cancer cells." (PMID 27269287, 2016).
bronchiolitis (1 paper, 2021). Inflammation of the bronchioles characterized by swelling of the bronchioles and mucus accumulation. "Furthermore, pharmacological inhibition of Arf6 activation by SecinH3, a potent inhibitor of Arf6 guanine nucleotide exchange factor (GEF), suppresses bronchiolitis with mucus hypersecretion induced by OVA challenge." (PMID 34423792, 2021).
cholangiocarcinoma (1 paper, 2023). A carcinoma that arises from the intrahepatic biliary tree (intrahepatic cholangiocarcinoma) or from the junction, or adjacent to the junction, of the right and left hepatic ducts (hilar cholangiocarcinoma). "A number of highly mutated cell signaling pathways are new to cholangiocarcinoma and possess immune-based functions including ADP-ribosylation factor 6 (ARF6) trafficking (FDR 0.047), Semaphorin 4D (SEMA4D) (FDR 0.047) and Rho-Roc signaling (FDR 0.049)." (PMID 37095160, 2023).
cholestasis (1 paper, 2015). Impairment of the bile flow caused by obstruction within the liver, or outside the liver in the bile duct system. "The right lobe of this and the remaining 27 explants with diffuse ductal hyperplasia, cholestasis, and fibrosis, demonstrated ARF6 staining which was similar to normal liver tissue (Fig 1Ciii)." (PMID 26379158, 2015).
colitis (1 paper, 2024). Inflammation of the colon. "C1orf106 is an inhibitor for the GEF of Arf6 and the IBD-associated mutation disrupts C1orf106, leading to increased Arf6 activation and risk of colitis." (PMID 38648480, 2024). "We therefore hypothesized that Sirt2 is involved in colitis by regulating Arf6 fatty-acylation and activation, thus influencing the integrity of intestinal epithelium." (PMID 38648480, 2024). "In a more physical context, we determined Arf6 activation and E-cadherin endocytosis in primary epithelial colon cells from DSS-induced colitis mice." (PMID 38648480, 2024).
deafness (1 paper, 2019). An inherited or acquired condition characterized by the complete loss of the ability to hear from one or both ears. "Moreover, ARF6-dependent trafficking has been recently implicated in inner-ear hair cell function, suggesting that membrane trafficking defects in hair cells can be implicated in TBC1D24-associated deafness." (PMID 30335140, 2019).
dyslipidemia (1 paper, 2023). "Our study demonstrates that the atheroprotection in Arf6 heterozygous mice was independent of changes in systemic dyslipidemia and associated with shear sensing, cell migration and proliferation." (PMID 37163513, 2023).
experimental autoimmune encephalomyelitis (1 paper, 2023). An autoimmune demyelinating disease of the central nervous system that is produced experimentally in animals by the injection of homogenized brain or spinal cord in Freund's adjuvant. "In addition, pharmacological treatment with an ARF6 inhibitor (NAV-2729) blocked ARF6 activation in an experimental autoimmune encephalomyelitis mouse model, enhancing BCNSB function, reversing EndoMT, and reducing disease progression." (PMID 37834383, 2023).
glomerular disease (1 paper, 2017). "Perhaps alteration of ARF6 activity is only relevant in a specific subset of glomerular disease patients." (PMID 28880939, 2017).
heart failure (1 paper, 2019). Inability of the heart to pump blood at an adequate rate to meet tissue metabolic requirements. "Blocking Arf6 in specific processes has been proposed as a potential target for therapeutic intervention to block cancer cell invasion and other aspects of oncogenesis and to improve endothelial barrier function in endotoxaemia and heart failure." (PMID 31060328, 2019).
hydrops fetalis (1 paper, 2017). Hydrops fetalis is a severe and challenging fetal condition usually defined as the excessive accumulation of fetal fluid within the fetal extravascular compartments and body cavities that manifests as edema, pleural and pericardial effusion and ascites. "Because impairment in lymphatic vascular formation causes hydrops fetalis with back skin edema, we examined the lymphatic vascular network formation in the back skin of Arf6−/− embryos by immunofluorescent staining for the specific marker of mouse LECs (mLECs) LYVE-1." (PMID 28900118, 2017).
Hyperglycemia (1 paper, 2026). An increased concentration of glucose in the blood. "Peripheral hyperglycemia-induced LPA upregulates Arf6-driven macropinocytosis of fucosylated CD147+ LG-EVs, which activates AKT/mTOR/4EBP1 signaling to promote SFR." (PMID 41362734, 2026).
idiopathic pulmonary hypertensive (1 paper, 2019). "Silencing of endothelial CLIC4 or inhibition of Arf6 activity with Sec7 inhibitor H3 (SecinH3) prevent development of pulmonary hypertension in preclinical models of the disease." (PMID 30582444, 2019). "Endothelial colony–forming cells from idiopathic pulmonary hypertensive patients showed upregulation of CLIC4 expression and Arf6 activity, suggesting potential importance of this pathway in the human condition." (PMID 30582444, 2019). "Arf6 is a novel effector of CLIC4 and a new therapeutic target in pulmonary hypertension." (PMID 30582444, 2019).
Infertility (1 paper, 2024). "ARF6 and ARF8 regulate the maturation of male and female floral organs in Arabidopsis thaliana, and the removal of these proteins in ARF6 ARF8 double mutants or plants over-expressing miR167 can lead to infertility." (PMID 38273235, 2024).